NLRP6 (NLR family pyrin domain containing 6)
Diseases named in the same sentence as NLRP6 in open-access papers (continued):
Sharing a sentence is not in itself a finding about the gene and the disease.
Streptococcus pneumoniae Infection (3 papers, 2021 to 2022). "Then, wild-type (WT) and NLRP6−/− mice were used as intranasal infection models to investigate the role of NLRP6 in the host against pneumococcal infections." (PMID 33918100, 2021). "Furthermore, the negative role of NLRP6 in Staphylococcus aureus and Streptococcus pneumoniae infection was found to be regulated by neutrophil recruitment as a higher number of neutrophils was detected in bacterial infected-Nlrp6−/− mice." (PMID 36224650, 2022).
alcoholic liver diseases (2 papers, 2022 to 2023). A disorder caused by damage to the liver parenchyma due to alcohol consumption. "In alcoholic liver disease, the gut microbiota and its components, including LPS and dsDNA, activate the TLR4/MyD88–ROS pathway in the portal circulation, thereby triggering NLRP6 inflammasome-mediated pyroptosis." (PMID 36969233, 2023).
Autoimmunity (2 papers, 2023). The occurrence of an immune reaction against the organism's own cells or tissues. "We have provided evidence that NLRP6-deficient mice have altered intestinal antibody titers and this most likely contributes to the modulation of the gut microbiota, such as by antibody-coating of microbiota, known to have important implications in autoimmunity, including type 1 diabetes." (PMID 36911699, 2023). "Our study has highlighted that, in the absence of NLRP6, CD103+ B cells, which have regulatory properties, are expanded in many lymphoid tissues and this novel subset of Breg contributes to immune tolerance to islet beta cell autoimmunity." (PMID 36911699, 2023).
Cerebral ischemia (2 papers, 2024 to 2025). Restriction of arterial blood supply to the brain associated with insufficient oxygenation to support the metabolic requirements of the tissue. "confirm that BRCC3 plays a crucial role in the activation of NLRP6 inflammasome and inflammasome‐associated inflammatory response and pyroptosis in cerebral ischemia/reperfusion injury." (PMID 38544474, 2024). "Studies have shown that cerebral ischemia/reperfusion injury caused by middle cerebral artery embolization promotes NLRP6 inflammasome activation, leading to the occurrence of neuronal pyroptosis, accompanied by the release of a large number of pro-inflammatory cytokines." (PMID 39877634, 2025).
depression (2 papers, 2022 to 2025). "In vivo and ex vivo studies in methamphetamine-exposed mice confirmed these results and showed that methamphetamine induces anxiety-like, cognitive impairment, and depression-like behavior, further linking astrocyte-specific NLRP6 signaling to methamphetamine-induced neuroinflammation." (PMID 39879739, 2025). "First, current studies on pyroptosis and neurological diseases are limited to NLRP3 and AIM2 inflammasomes, and the link between other types of pyroptosis-related inflammasomes, such as NLRC4, NLRP6, and depression, needs to be further investigated and elucidated." (PMID 35722622, 2022).
diabetes (2 papers, 2023 to 2026). "In summary, we present a novel regulatory B cell subset, characterized by the expression of CD103, increased in NLRP6 deficiency and are potent TGFβ- and IL-10 producers, all of which delayed and prevented diabetes development." (PMID 36911699, 2023). "To confirm whether continued NLRP6-deficient bacteria exposure influenced diabetes development, we co-housed NLRP6-sufficient and -deficient mice and observed their diabetes development." (PMID 36911699, 2023). "We observed NLRP6-/-NOD and NLRP6+/+ littermates for spontaneous diabetes, and observed significantly delayed and reduced T1D development in female NLRP6-/- mice with reduced immune infiltration of the pancreas compared to NLRP6+/+ mice." (PMID 36911699, 2023). "We believe that the increased gut permeability in the NLRP6-deficient mice leads to increased LPS in the circulation, which protects NOD mice from diabetes development." (PMID 36911699, 2023). "We found that NLRP6-/- B cells significantly delayed diabetes development in the Rag-/-NOD recipients, compared to the recipients that were co-transferred with NLRP6+/+ B cells." (PMID 36911699, 2023). "However, the absence of NLRP6 promoted a more permeable gut barrier, which may predispose the mice to type 1 diabetes development (as has also been suggested in humans); however, in contrast to published work, here, the mice with a more permeable gut were more protected from developing diabetes." (PMID 36911699, 2023). "Additionally, we studied mice at 12-16-weeks old, when some NLRP6+/+NOD, but not NLRP6-/-NOD mice, had developed diabetes." (PMID 36911699, 2023).
gastric tumors (2 papers, 2017 to 2023). "The qPCR results revealed that NLRP6 was down-regulated in 24/32 (75%) of primary gastric tumors compared to their nontumor counterparts (P<0.05)." (PMID 29340077, 2017). "Additionally, NLRP6 mRNA expression was evaluated in gastric tumor tissues and in the surrounding nontumor tissues from 32 surgical specimens." (PMID 29340077, 2017).
gastroenteritis (2 papers, 2013 to 2025). An inflammatory disorder that affects the upper and lower gastrointestinal tract. "Infections by enteric virus and intestinal inflammation are recognized as a leading cause of deadly gastroenteritis, and NLRP6 and NLRP9b signaling control these infection and inflammation." (PMID 39396665, 2025).
Hirschsprung disease (2 papers, 2022 to 2025). Hirschsprung disease (HSCR) is a congenital intestinal motility disorder that is characterized by signs of intestinal obstruction due to the presence of an aganglionic segment of variable extent in the terminal part of the colon. "The role of NLRP6 has been also studied in individuals with Hirschsprung’s associated enterocolitis (HAEC), which is the principal cause of death in patients with Hirschsprung’s disease (HSCR), a congenital disorder characterized by the absence of ganglion cells at the end of the bowel." (PMID 35650327, 2022). "Finally, reduced NLRP6 inflammasome expression in patients with congenital large intestine conditions and Hirschsprung’s disease, characterized by the absence of nerve cells in parts of the colon, suggests that NLRP6 may be protective in congenital gut diseases." (PMID 41062723, 2025).
kidney damage (2 papers, 2020 to 2022). "The results from animal data support our in vitro findings that the NLRP6 inflammasome, autophagy and ER stress play an important role in nicotine-induced kidney damage." (PMID 33114531, 2020). "However, in the nicotine-induced kidney damage model, where nicotine acted as an NLRP6 inflammasome activator, NLRP6 increased kidney injury by increasing release of ASC, active caspase-1, and IL-1β93." (PMID 35650327, 2022). "However, the relationship between NLRP6 and nicotine-induced kidney damage still remains unclear." (PMID 33114531, 2020).
liver cancer (2 papers, 2022 to 2023). An epithelial or non-epithelial malignant neoplasm that arises from the liver. "It indicates the harmful effect of C. albicans on liver cancer may be mediated by NLRP6, which provides a new target for the cancer treatment." (PMID 36246294, 2022). "Abnormal colonization of C. albicans increased the size and weight of liver cancer, affected the cancer cell metabolism, thus promoting the progression of liver cancer dependent on nucleotide oligomerization domain-like receptor family pyrin domain containing 6 (NLRP6)." (PMID 36246294, 2022).
rheumatoid arthritis (2 papers, 2021 to 2022). A chronic, systemic autoimmune disorder characterized by inflammation in the synovial membranes and articular surfaces. "An anti-inflammatory role of NLRP6 has been reported in rheumatoid arthritis patients in which NLRP6 was found to be downregulated in synovial tissues and fibroblast-like synoviocytes (FLSs) in rheumatoid arthritis patients compared with osteoarthritis patients." (PMID 33910012, 2021).
staphylococcus aureus infection (2 papers, 2022 to 2023). An infectious process in which the bacteria Staphylococcus aureus is present. "However, NLRP6 was shown to negatively regulate inflammation to S.p or to Staphylococcus aureus infections, suggesting a beneficial role of Nlrp6 depletion or inhibition in these secondary infections." (PMID 38146368, 2023). "In the defense against Streptococcus pneumoniae and Staphylococcus aureus infections, NLRP6 has a negative effect on the resistance to the infection in which the expression of NLRP6 can cause inflammation and tissue damage." (PMID 36556283, 2022).
ureteric obstruction (2 papers, 2021 to 2022). "To this end, we performed experimental unilateral ureteric obstruction (UUO) on Nlrp6+/+ and Nlrp6−/− mice." (PMID 33376129, 2021).
alcohol (1 paper, 2022). "In contrast, very little is known about the role of the NLRP6 inflammasome during alcohol-related chronic liver disease." (PMID 35053298, 2022).
alcohol abuse (1 paper, 2022). The use of alcoholic beverages to excess, either on individual occasions ("binge drinking") or as a regular practice. "To determine the impact of chronic alcohol abuse and NLRP6 inflammasome activity on liver disease and intestinal homeostasis, we employed a novel long-term variation of this chronic-plus-binge “NIAAA model” of alcohol consumption in mice." (PMID 35053298, 2022). "However, despite one report suggesting a protective role of the NLRP3 inflammasome during chronic alcohol treatment in mice, the impact of inflammasome activation, in particular the impact of the NLRP6 inflammasome, on ALD progression during long-term chronic alcohol abuse is unknown." (PMID 35053298, 2022).
Anxiety (1 paper, 2025). Intense feelings of nervousness, tension, or panic often arise in response to interpersonal stresses. "Although our findings align with the observed behavioral deficits, the specific contribution of NLRP6 inflammasome signaling to cognitive impairment and anxiety-like behavior requires further exploration." (PMID 39879739, 2025).
Bovine mastitis (1 paper, 2023). INFLAMMATION of the UDDER in cows. "Zophobas morio (Z. morio) hemolymph can decrease the levels of NLRP3, caspase-1 and NLRP6 and inhibit the secretion of IL-1β and IL-18, thereby attenuating E. coli- or Staphylococcus simulans (S. simulans)-induced pyroptosis; thus, it can be a new therapeutic candidate for bovine mastitis." (PMID 37845761, 2023).
brain tumours (1 paper, 2023). "To investigate the biological function of NLRP6 in vivo, we intracranially injected the indicated LN229 cells into nude mice to monitor the progression of brain tumours." (PMID 37770465, 2023).
cerebral edema (1 paper, 2022). "The reduction of AIM2 inflammasome and caspase-1 expression via cyclic GMP–AMP synthase antagonist A151, NLRP6 reduction via NLRP6 siRNA, and restraining NLRC4 activation via RGS2 all show the attenuation of cerebral edema." (PMID 35370546, 2022).
chronic kidney disease (1 paper, 2017). Impairment of the renal function secondary to chronic kidney damage persisting for three or more months. "Among the NLR family members (NLRP1, NLRP2, NLRP3, NLRP6, NLRP12, and NLRC4), NLRP3 deficient mice had less tubular injury, inflammation, and renal fibrosis in chronic kidney disease (CKD)." (PMID 29100270, 2017).
coinfection (1 paper, 2022). The simultaneous infection of a host by multiple pathogen species. "Thus, it looked like NLRP6 and IL-18 could be promising molecules to target early on in this coinfection to stop an overactive inflammatory response and to stop damage to the tissues." (PMID 36556283, 2022).
corneal infection (1 paper, 2019). A viral or bacterial infectious process affecting the cornea. "Since induction of inflammasomes triggers Caspase-1 activation, we next determined whether corneal infection with virulent HSV-1 strains would enhance the expression levels of one or several of the five major inflammasomes: NLRP3, NLRP6, NLRP12, IFI16/p204, and AIM2." (PMID 31367214, 2019).
cystitis (1 paper, 2021). Inflammation of the urinary bladder. "The mRNA expression levels of Nlrp6 and Casp11 were significantly increased in the cystitis rat model and in the acrolein-treated neurons." (PMID 34658764, 2021). "Therefore, we designed experiments to explore the neurotoxicity of CYP treatment in the bladder of rats by observing the functional and morphological changes of the bladder, and the alternations of NLRP6 inflammasome expression levels in a low-dose CYP-induced cystitis model." (PMID 34658764, 2021). "NLRP6, a non-canonical inflammasome components, has been predicted to be a useful therapeutic target in CYP-induced cystitis." (PMID 34658764, 2021).
endothelial dysfunction (1 paper, 2021). In vascular diseases, endothelial dysfunction is a systemic pathological state of the endothelium (the inner lining of blood vessels) and can be broadly defined as an imbalance between vasodilating and vasoconstricting substances produced by (or acting on) the endothelium. "Finally, it must be stressed that inflammasomes other than NLRP3, such as AIM2, NLRP1, NLRC4, and NLRP6, have not been thoroughly investigated so far in the context of the development of endothelial dysfunction and the impact on pathogenesis and progression of T2DM." (PMID 33546399, 2021).
enterovirus infection (1 paper, 2022). "NLRP6 was shown to inhibit enterovirus infection through the interferon pathway by binding to viral RNA via the RNA-decapping enzyme DHX15." (PMID 35216425, 2022). "Likewise, NLRP6 was found to prevent enterovirus infection, with increased viral load in knockout mice systemically infected with cerebral myocarditis virus or MNV in Nlrp6 knockout and control mice." (PMID 35216425, 2022).
familial Mediterranean fever (1 paper, 2024). Familial Mediterranean fever (FMF) is an autoinflammatory disorder characterized by recurrent short episodes of fever and serositis resulting in pain in the abdomen, chest, joints and muscles. "When not properly regulated, dysregulation of NLRP6 inflammasome activation manifests several diseases, which include familial Mediterranean fever caused by mutations in the pyrin‐coding gene MEFV, or cryopyrin‐associated periodic syndrome, caused by point mutations in Nlrp6 gene." (PMID 38644450, 2024).
glioblastoma (1 paper, 2023). The most malignant astrocytic tumor (WHO grade IV). "We further show that loss of NLRP6 suppresses cell proliferation, colony formation, cell migration, and tumour growth in glioblastoma cells in vitro and in vivo." (PMID 37770465, 2023). "In consistent with this hypothesis, NLRP6 expression level is negatively correlated with p85α expression level in human glioblastoma samples." (PMID 37770465, 2023). "Taken together, these results suggested that NLRP6 acts as an oncogene in glioblastoma." (PMID 37770465, 2023). "Moreover, NLRP6 expression is negatively correlated with p85α and PTEN in human glioblastoma." (PMID 37770465, 2023).
influenza (1 paper, 2022). An acute viral infection of the respiratory tract, occurring in isolated cases, in epidemics, or in pandemics; it is caused by serologically different strains of viruses (influenzaviruses) designated A, B, and C, has a 3-day incubation period, and usually lasts for 3 to 10 days. "Our findings indicated that NLRP6−/− mice were more resistant to Brucella Suis and Influenza coinfections since there was a lower systemic inflammation and bacterial load in the lung tissue after coinfection." (PMID 36556283, 2022). "We hypothesized that NLRP6 participates in the pathogenesis of the Influenza–bacterial coinfection and may be a useful therapeutic target." (PMID 36556283, 2022). "In addition, given that NLRP6 has an antiviral role in the intestines, it would be interesting to see if NLRP6 plays a protective or negative role in pulmonary host defense during Influenza infections." (PMID 36556283, 2022).
intestinal cancer (1 paper, 2017). "The NLR family member NLRP6 is highly expressed in intestinal tissue and can aid in diagnosing and determining the prognosis of patients with gastric and intestinal cancers." (PMID 29340077, 2017).
irritable bowel syndrome (1 paper, 2023). Irritable bowel syndrome (IBS) is a chronic functional condition of the lower gastrointestinal (GI) tract characterized by abdominal pain or discomfort and disordered bowel habit (diarrhea, constipation, or fluctuation between the two). "Also, a positive significant correlation between F. prausnitzii abundance and mRNA and protein expression of NLRP6 was found in rats in an induced model for irritable bowel syndrome (IBS)." (PMID 38163085, 2023).
kidney (1 paper, 2021). "Lastly, the discrepancy between our findings could relate to the difference in disease models—both UUO and NTS are chronic models of kidney injury, whereas the prior role for Nlrp6 was proposed to regulate acute kidney injury." (PMID 33376129, 2021).
kidney inflammation (1 paper, 2025). "Genetic deficiency of NLRP6 led to the upregulation of kidney extracellular signal-regulated kinase 1/2 (ERK1/2) and p38 mitogen-activated protein kinase phosphorylation, exacerbating AKI and kidney inflammation." (PMID 40827445, 2025).
lung carcinoma (1 paper, 2023). "From these two studies, which are the only ones to address the relationship between lung tumors and NLRP6, it can be inferred that NLRP6 may have a role in the development and unfavorable prognosis of lung cancer, which offers a focus for future study." (PMID 37415625, 2023).
lymph node metastasis (1 paper, 2017). "Analysis of clinicopathological parameters showed that high NLRP6 expression was strongly correlated with local lymph node metastasis (N stage, P=0.027), and TNM stage (P=0.018)." (PMID 29340077, 2017).
lymphoma (1 paper, 2025). A malignant (clonal) proliferation of B- lymphocytes or T- lymphocytes which involves the lymph nodes, bone marrow and/or extranodal sites. "In mouse embryonic fibroblast cell lines and human lymphoma cell line MBL‐1 stably expressing NLRP6 and treated with the synthetic dsRNA polyI:C, NLRP6 undergoes liquid–liquid phase separation and assembles a dsRNA‐NLRP6‐ASC speck leading to caspase‐1 activation." (PMID 39351983, 2025).
macular degeneration (1 paper, 2025). Loss of vision in the central portion of the retina (macula), secondary to retinal degeneration. "In the future, cell experiments and other methods should be used to clarify the precise regulatory pathways involving NLRP6, IL-1β and IL-18 in macular degeneration." (PMID 40837366, 2025). "Our findings show that the levels of NLRP6, IL-1β and IL-18 in the peripheral blood of patients with macular degeneration are increased." (PMID 40837366, 2025). "Our study found that the level of NLRP6 in patients with macular degeneration was significantly higher than that in healthy controls." (PMID 40837366, 2025). "Further analysis showed that patients with advanced disease (III+IV) had higher concentrations of NLRP6 than patients with early disease (I+II), which indicated that NLRP6 was related to the occurrence of macular degeneration and the progressive stage of the disease." (PMID 40837366, 2025).
Meniere disease (1 paper, 2025). A disease of the inner ear (labyrinth) that is characterized by fluctuating sensorineural hearing loss; tinnitus; episodic vertigo; and aural fullness. "The main purpose of this study is to explore the relationship between inflammatory corpuscles of NLRP6 and serum levels of inflammatory cytokines IL-1β and IL-18 in patients with Meniere’s disease (MD) to provide a new index basis for clinical diagnosis of MD." (PMID 40837366, 2025).
metastatic tumors (1 paper, 2022). "Moreover, several inflammasomes, including NLRP6, showed different expression levels between primary tumors and liver metastatic tumors." (PMID 36270983, 2022).